BAG5 (BAG cochaperone 5)
Diseases named in the same sentence as BAG5 in open-access papers (continued):
Sharing a sentence is not in itself a finding about the gene and the disease.
neuroblastoma (1 paper, 2020). Neuroblastoma (NB) is the most common solid, extracranial childhood tumor. "Because BAG5 expression was upregulated in stressed SH-SY5Y neuroblastoma cells, we next evaluated whether BAG5 expression is increased in a mouse model of PD." (PMID 33085644, 2020).
non-small cell lung carcinoma (1 paper, 2025). A group of at least three distinct histological types of lung cancer, including non-small cell squamous cell carcinoma, adenocarcinoma, and large cell carcinoma. "BAG5, a unique member of this family, contains multiple BAG domains, yet its role in non-small cell lung cancer (NSCLC) remains largely unexplored." (PMID 40787462, 2025).
ovarian tumors (1 paper, 2023). "As evidence of the potential effect of BAG5 on Akt stability, we found that tumors overexpressing BAG5 contained higher Akt levels in uterine and ovarian tumors." (PMID 38139359, 2023).
retinal degeneration (1 paper, 2017). Degeneration of the retina. "In particular, overexpression of Hsp70 could partly reverse retinal degeneration and necrosis reduced by knocking down of DJ-1a in Drosophila (results were not given), suggesting that Hsp70 and BAG5 exerted opposite effects on neuroprotective function of DJ-1." (PMID 28348719, 2017).
Stroke (1 paper, 2024). Sudden impairment of blood flow to a part of the brain due to occlusion or rupture of an artery to the brain. "Moreover, up- and downregulated genes were commonly confirmed by both configurations of the HD-tDCS-FN application, including insulin-induced gene 1 (Insig1) and bcl-2-associated athanogene 5 (Bag5), which are related to stroke insults." (PMID 38389833, 2024).
synucleinopathies (1 paper, 2020). "Considering that BAG5 negatively regulates multiple cell protective mechanisms involving intracellular alpha-synuclein processing, we wanted to further investigate the molecular pathways in which BAG5 may function to advance our understanding of BAG5 as a potential modulator of synucleinopathies." (PMID 32850835, 2020).
cancer (10 papers, 2010 to 2025). A tumor composed of atypical neoplastic, often pleomorphic cells that invade other tissues. "BAG5 is overexpressed in several cancer types and has been linked to poor prognosis in cancer patients." (PMID 40870378, 2025). "BAG5 is frequently overexpressed in many human tumors and the overexpression of BAG5 is associated with poor prognosis of cancer patients." (PMID 27807478, 2016). "As an initial insight into the deubiquitination/ubiquitination system linked to BAG5 expression in cancer patients in which the BAG5 is amplified, we identified a group of DUBs and E3 ligases, which are essential in cancer cells, preferentially linked to BAG5 overexpression." (PMID 38139359, 2023). "This duality might be important in the regulation of Akt in cancer patients overexpressing BAG5, which we found to be statistically linked to higher Akt expression." (PMID 38139359, 2023). "High expression levels of BAG5 are associated with poor prognosis in cancer patients." (PMID 27807478, 2016). "Western blot analysis also showed that BAG5 expression was significantly higher in most of NSCLC tissues compared with paired para-cancer tissues." (PMID 40787462, 2025). "To obtain an initial insight into the profile of DUBs and E3 ligases, we mined the TCGA cancer datasets, looking for those with a higher correlation with BAG5 expression." (PMID 38139359, 2023). "Since BAG5 amplification correlated with Akt1 protein expression, we identified and compared the top ten correlated DUBs and E3 ligases with BAG5 in general and in amplified BAG5 cancer patients." (PMID 38139359, 2023). "In this study, no Bag5 expression was detected in the benign biopsies while 3 out of the 4 cancer samples analyzed (75%) were positive for Bag5." (PMID 23448667, 2013). "Thus, we investigated the profile of deubiquitinases (DUBs) and E3 ligases coexpressed with BAG5 in cancer patients of the TCGA datasets in which the BAG5 gene was amplified." (PMID 38139359, 2023). "Additionally, it was demonstrated that miR-4454 and miR-127 suppress the cancer cells through regulation of BAG5 expression and over expression of BAG5 can neutralize the suppressive effect of miR-127 and miR-4454." (PMID 35821856, 2022). "In addition immunohistochemical analysis of Bag5 was performed on a tissue microarray containing benign and malignant prostate tissues from a core of 91 cancer cases." (PMID 23448667, 2013). "Furthermore, the authors concluded that BAG5 could be useful as a novel target to control cancer cell growth." (PMID 35821856, 2022). "Furthermore, our proteomic interactome suggests BAG5 may regulate translation through interaction with RNA-binding proteins such as IGF2BP1–3 and factors associated with EIF2α phosphorylation, which have been implicated in cancer cell metabolic control." (PMID 40787462, 2025). "A strong correlation was found between ASPP1 and BAG5 in almost all cancer types except LAML (R=-0.034) indicating that ASPP1 and BAG5 have strong relation in cancers." (PMID 39830645, 2024). "Saos2-R175H, Saos2-R248W, Saos2-R273H, Saos2-con cells and HCT116p53R248W/−, HCT116p53−/− cells with or without BAG5 knockdown by siRNA were treated with 5-FU, one of the most commonly used chemotherapeutic agent for human cancer." (PMID 27807478, 2016). "As for BAG5 and PLEKHF1, they have not been investigated in OS up to now, while their role in some other cancers have been documented." (PMID 35504036, 2022).
tumor (8 papers, 2013 to 2025). "Given the strong association of BAG5 with tumor progression, we next evaluated its functional role in NSCLC using genetic knockout strategies." (PMID 40787462, 2025). "In vivo, BAG5 knockout led to marked reductions in tumor weight, volume, and Ki67 expression in xenograft mouse models." (PMID 40787462, 2025). "Despite prior studies suggesting context-dependent roles for BAG5 in tumor biology, its specific functions and regulatory mechanisms in NSCLC remain largely undefined." (PMID 40787462, 2025). "To investigate the cellular functions enriched in BAG5+ tumor cells, we analyzed single-cell transcriptomic data from NSCLC epithelial cells." (PMID 40787462, 2025). "By combining single-cell transcriptomics, proteomics, phosphoproteomics, and functional validation in PDO/PDX models, we bridge the knowledge gap surrounding BAG5-mediated tumor pathways in NSCLC and provide novel insights with translational implications." (PMID 40787462, 2025). "We observed at the RNA level that only 13% of the BPH samples (2/15) expressed Bag5 compared to 59% tumor probes (16/27)." (PMID 23448667, 2013). "From the results of this work that Bag5 is a stress-inducible gene and it is anti-apoptotic, we would expect a tumor with high expression of Bag5 to be more aggressive and less responsive to stress-inducing chemotherapeutic agents." (PMID 23448667, 2013). "Based on the multi-omics data and functional analysis, the current study demonstrated that BAG5 was involved in a variety of tumor pathways, including metabolic reprogramming, mitochondria dynamics, metabolism of RNA and EMT, to facilitate proliferation and invasion of NSCLC." (PMID 40787462, 2025). "Given that GLUT3 is essential for aerobic glycolysis and tumor cell proliferation, this axis could be selectively exploited, especially in tumors with high BAG5 and GLUT3 co-expression." (PMID 40787462, 2025). "However, given that BAG5 expression was strongly enriched in tumor epithelial cells, downstream analyses focused on epithelial subclusters to investigate functional heterogeneity within this population." (PMID 40787462, 2025). "BAG5 might have both tumor-promoting and tumor-suppressive function in a cell-context dependent manner." (PMID 40787462, 2025). "These demonstrated circ_0008305 and BAG5 could exert tumor oncogenic roles while miR‐660 acted as a tumor suppressor in HCC." (PMID 33481351, 2021). "Notably, knockdown of BAG5 by shRNA greatly inhibited the growth of xenograft tumor formed by HCT116p53R248W/− but had a very limited effect for HCT116p53−/− tumors." (PMID 27807478, 2016). "Here again, increased Bag5 expression was found in the tumor compared to the benign cell lines." (PMID 23448667, 2013). "If this is the case, it would be worth investigating the use of Bag5 as a novel tumor biomarker." (PMID 23448667, 2013). "The expression level of BAG5 in tumor epithelial cells was significantly higher than that in other cell types, as well as than that in normal lung epithelial cells, suggesting that BAG5 may be associated with malignant progression of NSCLC and may have a specific role in tumor epithelial cells." (PMID 40787462, 2025). "Bag proteins like Bag1 and Bag3 have been implicated in tumor growth and survival but it is not known whether Bag5 also exhibits this function." (PMID 23448667, 2013). "These tumor types share molecular features such as EMT, metabolic reprogramming, and cell cycle deregulation, which is consistent with the phenotypes observed following BAG5 modulation in our NSCLC models." (PMID 40787462, 2025). "In addition, single cell transcriptome revealed the high co-expression of BAG5 and DRP1, the gene involved in fission of mitochondria, in NSCLC epithelial tumor cells." (PMID 40787462, 2025).
tumor (continued). "In parallel, BAG5 also modulates mitochondrial fission-fusion balance, as evidenced by increased MFN2 and decreased DRP1 expression upon BAG5 silencing, leading to enhanced mitochondrial fusion and reduced tumor aggressiveness." (PMID 40787462, 2025). "By reanalyzing public scRNA-Seq data sets (GSE119911), the current study identified heterogeneous expression of BAG5 in NSCLC tumor epithelial cells, which rationally explain the discrepancy between increased BAG5 expression and its lack of prognostic significance in the TCGA cohort." (PMID 40787462, 2025).
neurodegenerative disease (4 papers, 2011 to 2022). A disorder of the central nervous system characterized by gradual and progressive loss of neural tissue and neurologic function. "Finally, several proteins that are associated with neurodegenerative diseases were upregulated either during isolation (Pfn4, C1qb, Bag5 and Sv2c) or following regrouping (oxidative phosphorylation-associated genes such as Ndufc2)." (PMID 34650208, 2022). "Various studies have reported that the expression of BAG5 protein in the brain monitors the development of neurodegenerative diseases." (PMID 35821856, 2022). "However, further research is needed to understand the role of BAG5 in neurodegenerative diseases." (PMID 35821856, 2022).
myopathy (1 paper, 2024). A disease of the muscle in which the muscle fibers do not function properly. "Within this context, our analysis revealed correlations with several proteins, including BAG5, DNAJB4, and DNAJB5, which have plausible or confirmed roles in myopathy." (PMID 38392191, 2024).
BAG5 also shares sentences with these, for which no sentence is quoted: lung carcinoma (2 papers); schizophrenia (2); acephalic spermatozoa syndrome (1); advanced heart failure (1); benign prostatic hyperplasia (1); cardiac arrhythmia (1); endometriosis (1); Infertility (1); Left ventricular dilatation (1); osteosarcoma (1); prostate tumor (1); reproductive diseases (1); skin cancer (1); Ventricular arrhythmia (1).